MMP9 (matrix metallopeptidase 9)
Diseases named in the same sentence as MMP9 in open-access papers (continued):
Sharing a sentence is not in itself a finding about the gene and the disease.
tumor (continued). "The TAMs in BCCs induce COX-2 expression, which, in turn, results in a COX-2 dependent release of MMP-9, VEGF, and FGF that promotes tumor invasion." (PMID 31134198, 2019). "Consistent with tumor growth inhibition, the result showed that in tumors with depleted LPCAT1 the expression of PCNA, CD34 and MMP9 were diminished (P < 0.05)." (PMID 30791942, 2019). "C26 cells stimulation by either sICAM-1 administration or co-culture with LSECs results in tumor cell secretion of inflammatory PGE2 and IL-6, VEGF, uPA, MMP-2, MMP-9." (PMID 31511625, 2019). "Matrix metalloproteinases (MMP)-9 and MMP-2 proteins can actively mediate the dissemination of tumor cells to distant sites." (PMID 31013639, 2019). "The effective regulation by SPG-56 of the expression of metastasis-related proteins MMP2, MMP9, VEGF, Occludin, Claudin and STAT3 further confirmed the inhibition by SPG-56 of tumor metastasis." (PMID 30651572, 2019). "N-[4-(difluoromethoxy)phenyl]-2-[(4-oxo-6-propyl-1H-pyrimidin-2-yl)sulfanyl]-acetamide bound selectively to the MMP-9 HPX domain with KD = 2.1 μM and inhibited tumor growth and lung metastasis in MDA-MB-435 mouse models." (PMID 31214203, 2019). "Many upregulated genes in the heat map have been reported to promote tumor metastasis, such as FOSB, OLR1, S100A9, MMP9, and ANGPTL4 36-40." (PMID 31598162, 2019). "Pro- tumor neutrophils induce progression disease and release of CXCL1, MMP9, VEGF, and TNFα, whose reduction suppresses tumor growing." (PMID 31799175, 2019). "Gene expression of IL- 6, IL-10, CCL2, c-Myc, iNOS, CSF-1R, and MMP9 was elevated in all three of the in vitro TAM preparations which suggests that in vitro generated TAM are immunosuppressive and thus tumor promoting." (PMID 31138333, 2019). "Compare bilateral neoplasm subdivision group to one side neoplasm subdivision group, only levels of MMP-7 and MMP-9 showed significant differences (p < 0.05)." (PMID 31406154, 2019). "The recruited neutrophils present high expression of tumor-promoting genes such as TNF-α, CXCL1, MMP9, and VEGF." (PMID 31474975, 2019). "This in turn leads to an increase in tumor cell invasion and metastasis via phosphorylation of STAT3, which in turn promotes the transcription of matrix metallopeptidase 9 (MMP9) by binding to the MMP9 promoter." (PMID 31555295, 2019). "Compared with the control group, the tumor tissues from mice in the LOX inhibition group had reduced relative expression levels and enzyme activities of MMP-2 and MMP-9 (P < 0.05)." (PMID 31777578, 2019). "In previous studies of brain metastasis of breast and lung cancer, tumor cells were identified as the main destroyers of the blood brain barrier (BBB) via the production of MMPs (MMP1, MMP2, MMP3, and MMP9)." (PMID 30616691, 2019). "Taken together, the results demonstrated that miR-126 exerts tumor suppressing effects on the proliferation, migration and invasion by inhibiting MMP2, MMP9 and JAK2/STAT3 pathway via targeting ZEB1." (PMID 31007650, 2019). "MMP-9 and TIMP-1 were identified in tumor cells and in the tumor stroma compartment, as well as in macroscopically healthy mucous membrane." (PMID 31143300, 2019). "Analysis of the averaged optical intensities of MMP‐9 and TGF‐β signals in the tested specimens identified significantly higher value in the groups of malignant tumour (left)." (PMID 31264317, 2019). "As a result, the expression of matrix metallopeptidase 9 (MMP-9) and E-cadherin, which are characteristic proteins of tumor metastasis and invasion, are regulated." (PMID 30634497, 2019). "Of relevance, the kinetic variation of MMP-9 and VEGF levels in their local fold inductions showed a remarkable resemblance with the differential primary tumor growth between the TNBC models and the RNA-seq data." (PMID 31921184, 2019).
tumor (continued). "On the one hand, fibronectin forms a physical barrier for migrating cells; on the other hand, its interaction with tumor cell integrins, mainly with α5β1, triggers ECM proteolysis through secreting MMP-2 and MMP-9." (PMID 31344926, 2019). "In summary, during tumor invasion and metastasis, MMP-2 and MMP-9 are used to degrade the ECM and basement membrane so that tumor cells can detach, invade, and metastasize." (PMID 31777578, 2019). "MMP-2 and MMP-9 are members of the matrix metalloproteinase (MMP) family, which play an important role in angiogenesis, wound healing and tumor infiltration." (PMID 31214503, 2019). "The ability of RUNX2 to enhance the metastatic potential of tumor cells is largely based on its ability to regulate genes crucial to tumor progression including VEGF, MMP9, MMP13, OPN, SNAI 1–2, TWIST1 and TIMP13." (PMID 31395086, 2019). "MMP-9 expression in thyroid tissue was found to be associated with aggressive features and prognosis, including lymph node metastasis, tumor status, TNM stage and degree of tumor infiltration, likely via the ROCK/MMP-9 pathway." (PMID 33817161, 2019). "Tumor angiogenesis and lymphangiogenesis are dynamic processes that require the activation of MMPs mediated by VEGF (especially MMP-9) to induce the release of soluble KIT ligands (sKitL)." (PMID 31824776, 2019). "MMP-9 is functionally involved in VEGF activation, chronic angiogenesis induction, tumor growth at early stage." (PMID 31799175, 2019). "Interestingly, the selected phage bound to MMP-2 and MMP-9 also specifically homes to tumor vasculature, indicating that (i) that one, or both, of these MMPs is specifically expressed in tumor vasculature and (ii) they are available for phage binding from the circulation." (PMID 31140150, 2019). "An increase in serine proteases HTRA3, myeloblastin and lactotransferrin in all stages and metalloproteinases (MMP-9, ADAMTS4 and neutrophil elastase) in CC NM and CC M, supports degradation of the stroma surrounding the tissues as the tumor progresses." (PMID 31889941, 2019). "By virtue of its ability to upregulate MMP-9, STAT3 appears to robustly enhance tumor migration and invasion of MDA-MB-231 cells." (PMID 31456939, 2019). "Pro-tumor TANs supporting angiogenesis, were reported to express high level of the proangiogenic factors VEGF and MMP9 in a mouse model of melanoma and in liver tumorigenesis in zebrafish." (PMID 31616408, 2019). "The finding that CLU reduces MMP-9 and MMP-2 expression by inhibiting NF-κB is biologically relevant for PCa because these enzymes play a role in tumor dissemination by degrading ECM and basement membrane." (PMID 31885575, 2019). "Tumor size, serum levels of IFN-γ and IL-4 by ELISA, and Ki-67, MMP2, MMP9, VEGF and E-cadherin markers by IHC method were evaluated." (PMID 30127820, 2018). "Among the MMPs, MMP-9 and MMP-2 are abundantly expressed in various malignant tumors and are considered to play critical roles in tumor metastasis." (PMID 30574046, 2018). "An upregulation of either MMP9 or MMP14 in the stroma around the tumor cells is correlated with a more invasive phenotype, pointing to a critical role of MMPs in the tumor microenvironment." (PMID 29996539, 2018). "Matrix metalloproteinase-9 (MMP-9), whose expression is frequently dysregulated in cancer, promotes tumor growth, invasion, and metastasis by multiple mechanisms, including extracellular matrix remodeling and growth-factor and cytokine activation." (PMID 30500835, 2018). "The migration and the invasion processes of tumor cells can be regulated by many factors, such as BRMS1, E-cadherin, CXCL12, MMP9, Orai1, Stim1, TGF-β, and VEGF." (PMID 29316690, 2018). "In particular, matrix metalloproteinase-9 (MMP-9) is not only important for invasion and metastasis, but is also involved in tumour angiogenesis." (PMID 29973599, 2018). "By contrast, at the invasive front of the tumor, SNAIL, COX-2 and MMP-9 were retained as outcome variables of the model, in all patients." (PMID 29682175, 2018).
tumor (continued). "Specifically, N2 type TANs secrete a variety of cytokines, such as CCL2, neutrophil elastase (NE), hepatocyte growth factor (HGF), MMP9, and VEGF, which affect the growth, angiogenesis, invasion and metastasis of the tumor." (PMID 30157906, 2018). "The activity levels of pro-MMP-2, MMP-2, pro-MMP-9, and MMP-9 in tumor tissues were compared with the corresponding activities of the adjacent non-tumoral tissues when positive for lytic activity." (PMID 30060564, 2018). "It has been proposed that IL-33 stimulates cell migration through the expression of matrix metalloproteinases (MMP2/MMP9) via the ST2/ NF-κB pathway, thereby promoting cell invasion and tumor growth." (PMID 30483263, 2018). "In 110 patients with tissues from histologically proven LSCC the expression of CD45, CD11b, CD3, MMP-9 and COX-2 was semiquantitatively analyzed in stromal regions and tumor nests." (PMID 29492204, 2018). "HG-CD147 is highly expressed on the cell surface of a variety of tumor cells and can promote metastasis through inducing MMPs, especially MMP-2 and MMP-9, in tumor cells." (PMID 29719608, 2018). "Periostin is a driver of the EMT and induces expression of MMP-9, MMP-10, and MMP-13, resulting in the degradation of ECM, believed to be crucial for local tumor spread and/or metastasis via invasion and neovascularization." (PMID 29758011, 2018). "Activated Stat3 regulates tumour invasion by regulating the gene transcription of matrix metalloproteinase 2 (MMP-2), MMP-9, TGF-β1 and β-catenin, which also decreased after treatment with MSC-CM." (PMID 30297887, 2018). "This activity of the anti–MMP-9 antibody could also be contributing to the increased immune signatures in tumors, and is of notable translational relevance given that CXCR3 ligands in the tumor microenvironment are associated with response to adoptive transfer and checkpoint therapies." (PMID 30500835, 2018). "Overall expression of immunohistochemical markers in tumor cells were evaluated for the scoring for ANO1, MMP9, snail, and E-cadherin expression." (PMID 29416639, 2018). "In an in vivo tumour model, it was shown that that the protein, mRNA expression and/or activity of MMP-2, MMP-3, MMP-7 and MMP-9 were significantly higher in UVB-exposed skin and tumours of IL-12 knockout mice compared with wild-type mice." (PMID 29555826, 2018). "TGF-β promotes tumor invasiveness through MMP-2, MMP-9, MT-MMP1 and urokinase-like plasminogen activator is up-regulated in both pancreatic ductal adenocarcinoma and hepatocarcinoma." (PMID 30216977, 2018). "We have demonstrated that MMP-9 levels in frozen citrated plasma are stable if stored at − 80 °C, whereas MMP-9 levels in extracts from tumor tissue and tumor-free intestinal mucosa appear to increase with time." (PMID 29520667, 2018). "Metastasis process of the tumor was altered with the suppression in the expression of MMP-2, MMP-9 and urokinase-plasminogen activator (u-PA)." (PMID 30445746, 2018). "Tumor cell-derived TSLP induced AMs to express VEGF-A, platelet-derived growth factor-A, and MMP-9 thereby promoting lung metastasis." (PMID 30597969, 2018). "For instance, reactive astrocytosis as a result of surgical resection can promote tumor cell invasion via the secretion of distinct paracrine factors (e.g. TGF-α, CXCL12, S1P, GDNF, MMP-2, MMP-9)." (PMID 29728948, 2018). "The increased CCL2 promoted an influx of CD11b+ monocytes into the primary tumor that also had increased matrix metalloproteinase (MMP)-2, MMP-3, and MMP-9 expression." (PMID 30458886, 2018). "ECM metalloproteinases (MMPs), especially MMP-2 and MMP-9, cleave ECM components, degrade the basement membrane, and allow tumor cells to penetrate the adjacent matrix stroma." (PMID 29770331, 2018). "Recruited HPMo boosts angiogenesis by secreting MMP9 leading to release of matrix-bound VEGF-A, which amplifies the entry of more HPMo into tumours." (PMID 29367702, 2018).
tumor (continued). "Herein, we used ALT-C as a α2β1 integrin ligand to study the effect of ALT-C on MMP-9 and MMP-2 expression as well as on tumor cells, fibroblats and endothelial cell migration." (PMID 29713337, 2018). "The results of this study showed significant decrease in expression of VEGF, MMP2, MMP9, and CD31 factors in tumor-bearing mice under treatment with umbelliprenin compared to normal saline group." (PMID 30127820, 2018). "In conclusion, the data strongly indicated that the selected compound 16 inhibit tumor invasion and migration by repressing MMP-2 and MMP-9 at protein and mRNA levels." (PMID 29679218, 2018). "The MMP-9/VEGF/Tsp1 equilibrium is considered critical for tumour angiogenesis, since MMP-9 activates VEGF and Tsp-1 inhibits both MMP-9 activation and VEGF activity, and TIMP-3 is a potent angiogenesis inhibitor." (PMID 29914559, 2018). "The immunohistochemistry of p-AKT, MMP9, and PCNA of the xenograft tumor were also consistent with the previous experiments." (PMID 29642505, 2018). "Cotreatment with anti–MMP-9 and anti-PDL1 antibodies increased the proportion of CD3+ cells among tumor-infiltrating leukocytes, consistent with the observed increase in TCR diversity." (PMID 30500835, 2018). "One of the central signals in the TME that induces the pro-tumor TAN phenotype appears to be TGFβ, which induces the expression of CXCL1, VEGF, and MMP9, which are all factors leading to a more persistent tumor growth." (PMID 30349530, 2018). "For instance, inhibiting IL-17A at tumor sites significantly suppresses CD31, MMP9, and VEGF expression in the tumor, while activating its receptor (IL-17RA) promotes early tumor development." (PMID 29983876, 2018). "Matrix metalloproteinase-9 (MMP-9) is involved in degradation of ECM and vascular remodeling during tumor cell invasion." (PMID 30134822, 2018). "Once MMP-9 is inhibited, active CXCR3 ligands would accumulate in tumors and tumor-draining lymph nodes and promote trafficking of new Th1 CD4 T cells and effector CD8 T cells into tumors." (PMID 30500835, 2018). "In general, it is considered a suppressor of tumor angiogenesis and a potential tumor suppressor, in part through its inhibition of the gelatinases, MMP2 and MMP9." (PMID 29581841, 2018). "Because the PI3K/AKT signaling pathway has been shown to increase tumor invasion and metastasis by regulating MMP-2 and MMP-9, we investigated the role of this pathway in SEMA5A-induced invasion." (PMID 29977159, 2018). "In this regard, tumor-derived EVs harbor matrix-degradation proteases including matrix metalloproteinase-2 (MMP-2) and MMP-9, which correlated with tumor progression." (PMID 29696020, 2018). "Many of the studies conducted up to date on the MMP-9 in CRC are focused on the correlation of its expression in tissue and the clinicopathological features of the tumor." (PMID 30154846, 2018). "The elevation of tumor invasion is supported by our sequencing results that demonstrated TNFα up-regulates invasion-related genes of MMP1, MMP9, MMP14, LAMB3, and FGF2 which all have been previously reported to increase OSCC cancer invasion." (PMID 30018735, 2018). "Prior studies have shown that increased expression of key tumor microenvironment components such as collagen and MMP2/MMP9 are necessary for tumor epithelial extravasation." (PMID 30458886, 2018). "Some reports showed that the BRAF V600E can induce MMPs; a positive correlation has been reported between BRAF V600E and MMP-9 and MMP-2 expressions, both being correlated with tumor extrathyroid extension." (PMID 30509240, 2018). "In our study, the expression of HOXC6 was closely correlated with MMP-9 expression in HCC samples, suggesting that the tumor cells with high HOXC6 expression had high invasiveness." (PMID 29348394, 2018). "IL-6, CRP, and MMP-9 serum levels showed very similar trends, increasing concomitantly and reaching the highest values in stage IV CRC, indicating they are involved in tumor promotion and proliferation." (PMID 30154846, 2018).
tumor (continued). "Among them, MMP-9 is a kind of gelatinase in MMPs capable of degrading IV-type collagen in the ECM, which is involved in tumor invasion and metastasis." (PMID 29531823, 2018). "MMP-9 may antagonize T cell–mediated anti-tumor responses in tumors by shaping a local inflammatory cytokine/chemokine milieu hostile to effector T-cell infiltration, and by increasing the recruitment and/or activation of MDSCs and other suppressive myeloid infiltrates to the tumor." (PMID 30500835, 2018). "NF-κB binding sites were identified in the promoters of genes that encode several matrix metalloproteinases (MMPs) including MMP-2, MMP-9, and so forth, which degrade the extracellular matrix (ECM) to facilitate tumor cell invasion in tissues." (PMID 29361914, 2018). "Raw data from tumor volume and weight, ELISA (PGE2, IL-10 and VEGF) and morphometric quantification (VEGF, VEGFR-2, MMP-9 and COX-2)." (PMID 29609579, 2018). "As shown in the present study, significantly higher expression of CTHRC1, MMP-7 and MMP-9 was observed in a cohort of NSCLC sera and surgically resected tumour tissues." (PMID 29631554, 2018). "In the present study, IHC method was used to evaluate angiogenesis and metastasis in tumor tissues by MMP2, MMP9, VEGF, and CD31 markers assay." (PMID 30127820, 2018). "Among the MMPs, MMP1, MMP2, MMP9 and MT1-MMP produced by both stromal and tumor cells degrade and migrate through the ECM." (PMID 30241395, 2018). "We proved, by gelatin zymography, that all tumour cell lines secrete significant amounts of pro‐gelatinases MMP‐2 and MMP‐9." (PMID 29517849, 2018). "Expression of CD45, CD11b, CD3, MMP-9 and COX-2 in stroma and tumor was determined analyzing tissue microarrays of 110 patients with LSCC." (PMID 29492204, 2018). "The level of nuclear Gli1 is closely related to the pathological grade of tumours; invasive and metastatic abilities of the tumour; and levels of phosphorylated ERK1, phosphorylated ERK2 and MMP-9." (PMID 29899399, 2018). "At the same time, we compared the A2780/CP70 and OVCAR-3 cells, both in tumor and ALDH+ cells, finding that the expression level of MMP-9 protein was higher in A2780/CP70 than OVCAR-3 cells." (PMID 29914196, 2018). "Consistent with our mouse tumor model with reduced IGF-1R signaling, low IGF-1R is inversely correlated with IL-6, CCL2, and MMP9 expression in human tumors." (PMID 30458886, 2018). "Next, we determined potential correlations between CD45, CD11b, CD3, MMP-9 and COX-2 expression in stroma and tumor, respectively." (PMID 29492204, 2018). "Downregulation of matrix metalloproteinase 9(MMP9) and vascular endothelial growth factor (VEGF) A, which were up-regulated by IR injury and had potential in facilitating tumor cells invasion and angiogenesis, were confirmed in mice liver pretreated with PJ34." (PMID 29179487, 2017). "Several studies have shown that FAK/PI3K/AKT/mTOR signaling is involved in cell proliferation, differentiation, survival and tumor metastasis, and the signaling pathway is also involved in the regulation of MMP-2 and MMP-9." (PMID 29280977, 2017). "Although many of the details are unclear, neutrophils are thought to primarily propagate a pro-tumor environment by secreting molecules such as VEGF, MMP-9, and reactive oxygen species." (PMID 28418870, 2017). "The protein expression of Rab1B and MMP9 in the paired CRC and non-tumor tissues was examined by immunohistochemistry (IHC)." (PMID 28316326, 2017). "EMMPRIN is a surface multifunctional protein, expressed on both tumor and stroma cells, that can induce the expression of both VEGF and MMP-9 and enhance angiogenesis, probably through homophilic interactions." (PMID 29354134, 2017). "MMP-9 cleaves the components in the extracellular matrix, releasing VEGFA from its sequestered state and inducing angiogenesis around the tumor, as seen in hyperplastic islet of Langerhans." (PMID 28403223, 2017).